SCN9A (sodium voltage-gated channel alpha subunit 9)
Description:
Pore-forming subunit of Nav1.7, a voltage-gated sodium (Nav) channel that directly mediates the depolarizing phase of action potentials in excitable membranes. Navs, also called VGSCs (voltage-gated sodium channels) or VDSCs (voltage-dependent sodium channels), operate by switching between closed and open conformations depending on the voltage difference across the membrane. In the open conformation they allow Na(+) ions to selectively pass through the pore, along their electrochemical gradient. The influx of Na(+) ions provokes membrane depolarization, initiating the propagation of electrical signals throughout cells and tissues. Nav1.7 plays a crucial role in controlling the excitability and action potential propagation from nociceptor neurons, thereby contributing to the sensory perception of pain.
Synonyms: PN1; NENA; Nav1.7; NE-NA; ETHA; FEB3B; GEFSP7; HSAN2D; SFNP
Tractability: Small molecule: an approved drug acts on it; a structure with a bound ligand is known; a high-quality ligand is known; it belongs to a druggable protein family. Antibody: UniProt places it where antibodies can reach, with high confidence; its Gene Ontology location is reachable by antibodies, with high confidence; UniProt predicts a signal peptide or a membrane-spanning region; the Human Protein Atlas places it where antibodies can reach. PROTAC: UniProt records ubiquitination sites on it; ubiquitination databases record sites on it; a small molecule that binds it is known.
Target class: Voltage-gated ion channel; Voltage-gated sodium channel; Ion channel
Chemical probes: DS-1971a (high quality)
Gene: Protein-coding gene on chromosome 2 (166,195,185 to 166,376,001, reverse strand). Ensembl gene ENSG00000169432.
Subcellular location: Cell membrane; Cell projection, neuron projection; Cell projection, axon
Subcellular location (Human Protein Atlas): Actin filaments; Focal adhesion sites; Plasma membrane
Pathways (Reactome):
Developmental Biology: Interaction between L1 and Ankyrins
Muscle contraction: Phase 0 - rapid depolarisation
Sensory Perception: Sensory perception of sweet, bitter, and umami (glutamate) taste
Gene Ontology:
Molecular function: protein binding; voltage-gated sodium channel activity; monoatomic cation channel activity; monoatomic ion channel activity
Biological process: action potential propagation; membrane depolarization during action potential; neuronal action potential; sensory perception of pain; cardiac muscle cell action potential involved in contraction; sodium ion transmembrane transport; action potential; circadian rhythm; detection of mechanical stimulus involved in sensory perception; detection of temperature stimulus involved in sensory perception of pain; monoatomic ion transport; sodium ion transport; transmembrane transport
Cellular component: axon terminus; node of Ranvier; plasma membrane; voltage-gated sodium channel complex; axon; membrane; neuron projection
Genetic constraint (gnomAD): Loss-of-function variants: 94 observed, 130.54 expected, observed/expected ratio (o/e) 0.72, 90% interval 0.61 to 0.86. The upper end of that interval is the gene's LOEUF score, 0.86, which puts it in group 3 of 6, group 1 being the genes least tolerant of losing a copy. Missense variants: 1,898 observed, 2,053.7 expected, observed/expected ratio (o/e) 0.92, 90% interval 0.89 to 0.96. Synonymous variants: 689 observed, 699.78 expected, observed/expected ratio (o/e) 0.98, 90% interval 0.92 to 1.05.
Gene-disease validity (ClinGen):
ClinGen rates the evidence that SCN9A causes each of these diseases.
epilepsy (autosomal dominant): Refuted. A brain disorder characterized by episodes of abnormally increased neuronal discharge resulting in transient episodes of sensory or motor neurological dysfunction, or psychic dysfunction.
Homologues: Orthologues: chimpanzee SCN9A (99% identical), macaque SCN9A (98% identical), pig SCN9A (95% identical), dog SCN9A (94% identical), rabbit SCN9A (94% identical), mouse Scn9a (93% identical), rat Scn9a (93% identical), guinea pig SCN9A (92% identical). Paralogues in human: SCN2A (78% identical), SCN1A (77% identical), SCN3A (77% identical), SCN8A (71% identical), SCN4A (62% identical), SCN5A (62% identical), SCN10A (55% identical), SCN11A (47% identical), SCN7A (47% identical), CACNA1A (24% identical), CACNA1B (24% identical), CACNA1C (24% identical), and 14 more.
Diseases named in the same sentence as SCN9A in open-access papers:
SCN9A is named in the same sentence as 171 diseases in open-access papers, as found by Europe PMC text mining. Sharing a sentence is not in itself a finding about the gene and the disease. The quoted sentences say what the papers report.
paroxysmal extreme pain disorder (100 papers, 2008 to 2026). Paroxysmal extreme pain disorder is a rare disorder of abnormal pain sensation. "Gain-of-function mutations in SCN9A can produce two distinct inherited pain syndromes: primary erythromelalgia (PE) and paroxysmal extreme pain disorder (PEPD; OMIM #167400)." (PMID 41562815, 2026). "Mutations in the SCN9A gene, which encodes NaV1.7, are linked to rare inherited pain disorders, ranging from congenital insensitivity to pain to paroxysmal extreme pain disorder, highlighting its importance in human nociception." (PMID 41246666, 2025). "Kim D.T., Rossignol E., Najem K., Ospina L.H. Bilateral congenitalcorneal anesthesia in a patient with SCN9A mutation, confirmedprimary erythromelalgia, and paroxysmal extreme pain disorder.J." (PMID 39944808, 2024). "Variants in SCN9A are associated with primary erythromelalgia, paroxysmal extreme pain disorder, or insensitivity to pain, and variants in NLRP12 are associated with familial cold-induced autoinflammatory syndromes." (PMID 39276275, 2024). "Perhaps most strikingly, SCN9A-LOF causes paroxysmal extreme pain disorder, yet SCN9A-GOF leads to congenital insensitivity to pain." (PMID 36877742, 2023). "Mutations in SCN9A gene encoding for Nav1.7 are associated with pain disorders such primary hereditary erythromelalgia and paroxysmal extreme pain disorder." (PMID 36727110, 2023). "GOF mutations in the SCN9A gene, that result in hyperexcitable NaV1.7 channels, are associated with debilitating pain conditions, such as paroxysmal extreme pain disorder and familial erythromelalgia." (PMID 36891145, 2023). "Paroxysmal extreme pain disorder (PEPD) is similar to erythromelalgia also caused by a gain-of-function mutation of SCN9A." (PMID 35655042, 2022). "Functional mutations of the SCN9A genes are associated with many genetic diseases, including congenital pain insensitivity, primary limb pain erythema, paroxysmal extreme pain disorder, and small fiber neuropathy." (PMID 36052366, 2022). "Patients with a rare, chronic pain conditions such as primary erythromelalgia or paroxysmal extreme pain disorder exhibit gain of function mutations in SCN9A." (PMID 35295464, 2021). "As of 2019, 30 mutations in SCN9A genes had been described in inherited erythromelalgia and 13 in paroxysmal extreme pain disorder." (PMID 35295464, 2021). "Seven of them presented clinical manifestation of paroxysmal extreme pain disorder, of which and in four were identified missens mutations in the SCN9A gene (NM_002977.3:c.3892G > T)." (PMID 32404070, 2020). "Gain-of-function (GOF) mutations in SCN9A, encoding Nav1.7, cause inherited erythromelalgia and paroxysmal extreme pain disorder, rare familial diseases associated with excruciating pain." (PMID 32295642, 2020). "Loss-of-function mutation of the SCN9A gene that codes for Nav1.7 leads to congenital insensitivity to pain, whereas SCN9A gain-of-function mutations causes paroxysmal extreme pain disorder and primary erythromelalgia." (PMID 33584315, 2020). "In contrast, the SCN9A gain-of-function mutations cause genetic painful neuropathies such as small fiber neuropathy, primary erythromelalgia and paroxysmal extreme pain disorder." (PMID 30233376, 2018). "This mutation resulted in an SCN9A channelopathy that is most consistent with a diagnosis of paroxysmal extreme pain disorder." (PMID 27525141, 2016). "Several SCN9A sodium channelopathies have been recognized as the cause of rare painful dysautonomic syndromes such as paroxysmal extreme pain disorder and primary erythromelalgia." (PMID 22348792, 2012). "A NaV1.7 gain-of-function mutation in SCN9A, is linked to the human condition “familial rectal pain syndrome” now renamed “paroxysmal extreme pain disorder”." (PMID 27713376, 2010).
paroxysmal extreme pain disorder (continued). "Mutations in the SCN9A gene can be categorized as gain-of-function mutations (increased Nav1.7 activity), causing paroxysmal extreme pain disorder (PEPD) and erythromelalgia (EM); or loss-of-function mutations (reduced Nav1.7 activity), causing congenital insensitivity to pain (CIP)." (PMID 40283194, 2025). "First, gain-of-function mutations in the gene SCN9A that encodes the α-subunit of NaV1.7 were shown to underlie inherited pain disorders such as erythromelalgia and paroxysmal extreme pain disorder; these syndromes are characterised by burning pain and redness in the extremities." (PMID 39057947, 2024). "Notably, gain-of-function mutations within Scn9a, the gene encoding NaV1.7, underlie distinct human pain syndromes such as inherited erythromelalgia and paroxysmal extreme pain disorder." (PMID 38894876, 2024). "For example, SCN9A, for which dominant mutations may cause paroxysmal extreme pain disorder (PEXPD; MIM 167400), whereas biallelic mutations cause congenital insensitivity to pain (CIP; MIM 243000), which appears to be diametrically opposite phenotypes." (PMID 36140801, 2022). "Mutations in the SCN9A gene which lead to a gain of Nav1.7 function are associated with primary erythromelalgia and paroxysmal extreme pain disorder, while mutations in the SCN9A gene which lead to a loss of Nav1.7 function are associated with congenital insensitivity to pain." (PMID 29678208, 2018). "Gain-of-function mutations in SCN9A gene that encodes the voltage-gated sodium channel NaV1.7 have been associated with a wide spectrum of painful syndromes in humans including inherited erythromelalgia, paroxysmal extreme pain disorder and small fibre neuropathy." (PMID 28235406, 2017). "Background and Clinical Significance: Paroxysmal extreme pain disorder (PEPD) is an extremely rare autosomal dominant sodium channelopathy caused by SCN9A gain-of-function variants." (PMID 41562815, 2026). "Loss-of-function mutations of SCN9A were associated with congenital insensitivity to pain, while gain-of-function mutations of this gene were associated with neuropathic pain syndromes, including erythromelalgia, paroxysmal extreme pain disorder, and small-fiber neuropathy." (PMID 34947986, 2021). "Mutations in SCN9A were reported in three disorders, autosomal dominant primary erythermalgia (PE), paroxysmal extreme pain disorder (PEPD), and autosomal recessive channelopathy-associated insensitivity to pain (CIP)." (PMID 32466254, 2020). "Two inherited human neuropathic pain conditions, erythermalgia and paroxysmal extreme pain disorder (PEPD), are associated with various missense (gain of function) mutations in SCN9A, the gene encoding the human Nav1.7 channel." (PMID 25285069, 2014). "In humans, the loss of function mutation of the SCN9A gene that codes for NaV1.7 is linked to channelopathy-associated insensitivity to pain (CIP), while SCN9A gain of function mutations cause paroxysmal extreme pain disorder and primary erythromelalgia." (PMID 26690478, 2015). "In addition to PE, mutations in SCN9A gene can also result in paroxysmal extreme pain disorder (PEPD; OMIM 167400) and congenital insensitivity (or indifference) to pain (CIP; OMIM 243000)." (PMID 23383113, 2013). "Gain-of-function mutations in the gene encoding the α subunit of NaV1.7 (SCN9A) underlie two painful neuropathies known as paroxysmal extreme pain disorder (PEPD) and inherited erythromelalgia (IE), whereas loss-of-function mutations in SCN9A result in a congenital indifference to all forms of pain." (PMID 22069579, 2010). "Heterozygous missense mutations in several other voltage-gated sodium channel genes have been associated with BrS (SCN5A: MIM 600163), familial episodic pain syndrome FEPS3 (SCN11A; MIM 604385), primary erythermalgia, and paroxysmal extreme pain disorder (SCN9A; MIM 603415)." (PMID 36140801, 2022).
paroxysmal extreme pain disorder (continued). "More than 70 mutations on SCN9A have been associated with various clinical phenotypes, among which are pain disorders including gain-of-function disorders PE and paroxysmal extreme pain disorder (PEPD) as well as loss-of-pain disorder congenital insensitivity to pain (CIP)." (PMID 26419464, 2015). "Paroxysmal extreme pain disorder (PEPD, formerly known as familial rectal pain syndrome), is caused by gain of function mutations in SCN9A that alter the biophysical properties of the Nav1.7 channel." (PMID 32601768, 2020). "In addition to being associated with SFN, gain-of-function mutations in the SCN9A- gene have been described in the following human pain disorders: inherited erythromelalgia (IEM) and paroxysmal extreme pain disorder (PEPD)." (PMID 27363506, 2016). "In humans, mutations in the SCN9A gene (which encodes Nav1.7) are associated with three known pain disorders: channelopathy-associated insensitivity to pain (CIP), paroxysmal extreme pain disorder (PEPD), and primary erythermalgia (PE)." (PMID 21345196, 2011). "Paroxysmal extreme pain disorder (PEPD) is an autosomal dominant painful neuropathy with many, but not all, cases linked to gain-of-function mutations in SCN9A which encodes voltage-gated sodium channel Nav1.7." (PMID 18803825, 2008). "Heterozygous (monoallelic) gain of function SCN9A mutations is associated with multiple phenotypes including small nerve fiber neuropathy (SFN), inherited erythromelalgia (IEM), paroxysmal extreme pain disorder (PEPD), and a novel syndrome of pain dysautonomia." (PMID 27525141, 2016). "Mutations in SCN9A cause three human pain disorders: bi-allelic loss of function mutations result in Channelopathy-associated Insensitivity to Pain (CIP), whereas activating mutations cause severe episodic pain in Paroxysmal Extreme Pain Disorder (PEPD) and Primary Erythermalgia (PE)." (PMID 20635406, 2010).
erythromelalgia (86 papers, 2007 to 2025). A rare neurovascular peripheral pain disorder due to the intermittent blockage of the blood vessels, usually in the lower extremities or hands. "Mutations in SCN9A can result in congenital insensitivity to pain or inherited erythromelalgia, a disorder characterized by severe burning pain." (PMID 40141103, 2025). "Human genetic studies have highlighted the importance of these channels: gain-of-function mutations in SCN9A (Nav1.7) cause erythromelalgia (severe burning pain), while loss-of-function mutations cause congenital insensitivity to pain." (PMID 41155158, 2025). "For example, gain-of-function mutations in the SCN9A gene encoding voltage gated sodium ion channel Nav1.7 have been shown to cause Inherited Erythromelalgia (IEM)." (PMID 38581069, 2024). "The pathophysiology of inherited erythromelalgia associated with SCN9A variants has received extensive study using sodium channel electrophysiology in vitro." (PMID 37628281, 2023). "For example, a pair of sisters with Inherited Erythromelalgia carry the pathogenic SCN9A p.Ile848Thrwith autosomal dominant pattern of inheritance." (PMID 36895957, 2023). "Two sisters with severe erythromelalgia, present since childhood, have the same pathogenic variant in SCN9A p.Ile848Thr." (PMID 36895957, 2023). "The occurrence of erythromelalgia is related to the function-enhancing mutation of the NaV1.7 sodium channel gene SCN9A, therefore, sodium channel blockers are the most common pharmacotherapy targeting PEM." (PMID 36052366, 2022). "On the other hand, gain-of- function variants in SCN9A (encoding Nav1.7) are present in a few pain disorders, such as erythromelalgia and small-fiber neuropathy." (PMID 35419564, 2022). "Loss-of-function mutations in the human gene SCN9A encoding the Nav1.7 α subunit result in a congenital inability to experience pain, while gain-of-function mutations in SCN9A lead to inherited erythromelalgia and paroxysmal extreme pain disorder." (PMID 28880874, 2017). "Both gain and loss of function mutations of the SCN9A gene, which encodes the Nav1.7 α-subunit, have been associated with pain syndromes, including erythromelalgia." (PMID 25741286, 2015). "Inherited erythromelalgia (IEM) has been shown to be due to gain-of-function mutations in the SCN9A gene encoding the voltage-gated sodium channel Nav1.7 that is selectively expressed in sensory and autonomic neurons." (PMID 22365309, 2012). "Since then, genetic investigations of families where erythromelalgia was present have revealed that this disorder was caused by more than 20 different mutations of the SCN9A gene." (PMID 24278716, 2012). "While the precise mechanism of AZ106 remains unconfirmed, personal communication with AstraZeneca suggests it acts as a non‐specific Nav channel inhibitor, targeting proteins synthesised by SCN1‐10A and SCN1‐10B, including SCN9A which encodes the NaV 1.7 channel, implicated in erythromelalgia." (PMID 40415465, 2025). "Individuals with loss‐of‐function mutations in SCN9A exhibit congenital insensitivity to pain, while gain‐of‐function mutations cause chronic pain conditions such as paroxysmal extreme pain disorder and inherited erythromelalgia (IEM)." (PMID 40415465, 2025). "Gain-of-function (GoF) mutations in SCN9A, the gene that encodes the voltage-gated sodium channel subunit NaV1.7, are associated with inherited erythromelalgia (IEM, presenting with pain and erythema of the extremities) and increased sensory neuron spontaneous activity in vivo and in vitro." (PMID 37792955, 2023). "This hypothesis has been supported by observations in patients with inherited erythromelalgia caused by different point mutations in SCN9A." (PMID 32047194, 2020).